CD4 (CD4 molecule)
Diseases named in the same sentence as CD4 in open-access papers (continued):
Sharing a sentence is not in itself a finding about the gene and the disease.
infection (continued). "Interestingly, the abundance of IL-17+ CD4+ T cells remained unchanged between groups, suggesting that the adaptive immune response, in terms of IL-17 production, may not be significantly altered by super-infection at this early time point." (PMID 39949778, 2025). "Additionally, the type of immune response induction, whether due to infection, vaccination, or a combination of vaccination and infection, did not significantly affect the levels of the S protein-specific CD4 T-cells, as demonstrated by the geometric mean values (GMV, Table E7)." (PMID 41280926, 2025). "During the acute phase of infection, both spike- and non-spike–specific cTFH frequencies in children increased with age, as was observed for total SARS-CoV-2–specific CD4+ T cells." (PMID 40906527, 2025). "Similar to CD4+ T cells, we observed no significant changes in peripheral CD8+ T cell frequencies throughout infection or in the context of ART." (PMID 40504034, 2025). "Whereas embelin significantly reduced the percentage of CD19+ B cells 7 days after infection, a timepoint at which most surviving B cells are EBV infected, it did not significantly reduce CD56+ NK, CD4+, or CD8+ T cell frequency." (PMID 40674368, 2025). "In the absence of CD4+ T cells, DCs alone are generally insufficient to drive optimal CD8+ T cell responses, except in certain infections." (PMID 40279312, 2025). "As in all nonproducers, CD4 was strongly downregulated in these two clones, limiting the possibility that the 2-LTR circles resulted from infection." (PMID 40598490, 2025). "We have previously studied the expression of several activation markers in the same PBMC samples and shown that a robust activation of CD4 + and CD8 + T cells was induced during the course of the disease in AV-infected animals but not during fatal infection." (PMID 40245043, 2025). "While among group of nadir CD4+ T cell count < 300, HIV-1 total DNA copies at each time point was not correlated with infection duration and S/CO of RBD-specific-IgG at each time point." (PMID 41390617, 2025). "The frequencies of SARS-CoV-2–specific CD4+ and CD8+ T cells were not altered by breakthrough infection in either pregnant or lactating groups." (PMID 40693463, 2025). "In contrast to CD4 T cells, differences in global CD8 T cell profiles did not reliably discriminate pre- vs post-transplant, development of infection, or receipt of ATG." (PMID 40475763, 2025). "Most patients, including those treated with rituximab, developed a robust CD4+T cell response against the SARS-CoV-2 Spike protein, even after a non-severe infection." (PMID 40617588, 2025). "Surprisingly, although not statistically significant, the CD4-depleted group had higher levels of IP-10 in serum in comparison with the undepleted group by days 3 and 7 post DENV2 infection." (PMID 41295476, 2025). "Taken together, these findings suggest that, at least in this infection setting, IFN-γ derived from group 1 ILCs is not directly involved in CD4+ T cell polarization." (PMID 40169810, 2025). "7–8 days after infection, MDV progression switches from cytolytic phase to latency without producing infectious progeny in activated CD4+ T cells and infected B cells." (PMID 40241721, 2025). "In untreated early infection after PHI, immune activation increases over time, and CSF CD4+ T cell activation but not monocyte activation correlates with CSF HIV RNA." (PMID 40070827, 2025). "Finally, frequency of CSF CD4+ T-cell activation but not CD8+ T-cell activation or monocyte sub-phenotypes was independently associated with CSF HIV RNA prior to ART, suggesting that in the early stages of infection, T cell infection is an important determinant of viral replication within the CNS." (PMID 40070827, 2025).
infection (continued). "Thus, the infection establishment bottleneck in the airways was not greatly affected by CD4 or CD8α depletion, although the few Mtb that entered the lung parenchyma were uncontrolled in the absence of CD4 T cells or CD8α+ lymphocytes and disseminated within the lung and to the LNs." (PMID 39912921, 2025). "Given a lack of a murine infection model for HKU-1 and to mimic HKU-1 immunity, mice were primed with either Addavax alone, a peptide pool spanning the HKU-1 spike (to prime CD4 T cells) or the HKU-1 spike protein (to prime antibody, memory B and CD4 T cells)." (PMID 41315254, 2025). "Asymptomatic HIV/Leish co-infected subjects seemed to be controlling both infections: this group did not have any VL symptoms and had similar HIV viral loads, CD4+ and CD8+ T cell counts in comparison to HIV subjects." (PMID 40096173, 2025). "Third, our analysis focused on selected immune compartments (IgG antibodies, CD4+ T cells, circulating cytokines) and did not assess potentially relevant actors such as cytotoxic CD8+ T cells, local innate immunity at infection sites, or mucosal IgA responses." (PMID 41357245, 2025). "CD4+ TRM cells express CD44 and CD69, with or without CD103, lack CD62L expression, and reside in the respiratory tissues following infection, poised to respond rapidly upon re‐exposure." (PMID 40629997, 2025). "Strikingly, a significant increase in IL-17A expression was measured in lung tissue from mice transferred to lung CD3+CD4+ T cells compared with other groups, whereas no significant increase in IFN-γ expression was observed post infection." (PMID 39556597, 2024). "The same trend for MHC-II expression on live CD3+ cells was observed in live CD4+ T cells; MHC-II was significantly increased on days 20 and 30, but there was no detectable difference on day 6 post-686 infection." (PMID 39066253, 2024). "We also found a negative correlation between CD4+ TEM cell counts at admission and the duration of ICU stay, time to extubation, and infection marker PCT." (PMID 39266539, 2024). "IL-2 is primarily produced by activated CD4+ and CD8+ T cells and this data suggests a higher level of T cell activation in the spleens of non-survivors early after infection." (PMID 39513496, 2024). "For example, CD4+ T cells, but not monocytes, upregulated OAS1, OAS2, and DDX58 upon infection in all animals." (PMID 38317183, 2024). "At 8 d post primary infection, CD8+ T cells were predominantly directed at the A1/ORF1a1637 epitope, with an absence of B35/S321+CD8+ and DR15/S751+CD4+ T responses." (PMID 39284068, 2024). "Antibody depletion of CD4 T cells, CD8 T cells and neutralization of IFN-γ showed that CD4 T cells and IFN-γ, but not CD8 T cells, were important for protection against primary infection and secondary challenge with B. microti." (PMID 38392861, 2024). "The same did not occur with the TNF-α-producing CD4+ T lymphocytes; even though TNF-α is necessary to resolve the infection, this cytokine is related to liver damage." (PMID 38690280, 2024). "Compared to mice without pre- and post-infection, the A2l19f RSV-infected group exhibited higher IL-2+ expression in both CD4+ and CD8+ cell populations with peptide stimulation." (PMID 38629077, 2024). "We observed no quantitative difference in the number of CD4+ and CD8+ T cells between low and high dose infection, but a significant shift from a Th1 to a Th2 response and a lower amount of CD8+ effector T cells after high dose IAV infection." (PMID 38979428, 2024). "Unlike antibody levels, baseline frequencies of spike-specific CD4 or CD8 T cells were equally low in individuals with and without prior infection and both groups showed a similar increase after bivalent vaccination." (PMID 38594497, 2024). "The positivity of 11 samples collected at early infection was significantly increased in the presence of SARS-CoV-2 N antigen; p = 0.0186 in CD8+, but not in CD4+ T-cells (p = 0.0830)." (PMID 38543812, 2024).
infection (continued). "After infection, the serum AST concentrations in HHD mice lacking CD4+ and CD8+ T cells remained normal, whereas the AST concentrations increased in HHD mice." (PMID 39256346, 2024). "Studies in resistant C57Bl/6 mice have shown pre-existing effector CD4 T cells (CD44+CD62L−T-bet+Ly6C+ effector (TEFF)) generated by ongoing chronic infection and that these are short-lived if there is no infection." (PMID 39201440, 2024). "A significant increase in naïve CD4+ and CD8+ αβ T-cell counts was observed throughout the course of the study in subjects without a previous natural infection." (PMID 38793803, 2024). "On the other hand, CD4+ cell depletion did not significantly affect B1 B cells, CD69+ B1 B cells, or expression of CD69 on B1 B cells 2 days post-infection." (PMID 38715601, 2024). "CD4+/CD8 + ratio showed no relation with severity in our group, suggesting a complementary effect of other immune cells in the process of infection." (PMID 38678181, 2024). "However, there were no significant increases observed in the numbers of CD8+ T cells expressing IFN-γ or CD4+ T cells expressing GrzB, indicating that sequential infection may not globally affect the polyfunctionality of these cellular subsets after IM vaccination." (PMID 39356719, 2024). "There is now more data supporting the concept that patients with low CD4 count counts but without HIV (some of whom also have low ratios) are vulnerable to specific and severe infections as well as certain cancers." (PMID 39728019, 2024). "While Vpr significantly enhances infection of macrophage-containing cultures, primarily by enhancing cell-to-cell transmission, it does not substantially affect HIV infection in cultures of CD4+ T cells that lack macrophages." (PMID 38951492, 2024). "In addition, we examined whether the phenotype encoded in the viral sequences in the pool of long-lived cells, like viruses typically found in the blood throughout untreated infection, are adapted to entering CD4+ T cells and not macrophage (i.e. are T cell-tropic)." (PMID 38422171, 2024). "In contrast, CD32 was nearly undetectable on CD4 T cells (0.18% CD32+ cells) that had been infected following isolation from PBMCs by negative selection, despite comparable overall HIV-1 GFP infection levels (right)." (PMID 38579727, 2024). "Post infection, both transferred SMARTA PEP-WT and SMARTA PEP-619WW CD4 T cells expanded, regardless of host genotype." (PMID 38512979, 2024). "Antibody titers, CD4 and CD8 T cell responses of the individuals infected before their vaccination were similar to those with no prior documented infection." (PMID 39902042, 2024). "As with antibody levels, percentages of spike-specific CD4+ and CD8+ T cells after bivalent BA.4/5 vaccination increased in both patients with and without prior infection." (PMID 38326340, 2024). "No change in CD4+ and CD8+ T cell percentages was observed after the infection of both WT and TIGIT-KO mice while NK cell percentages isolated from kidneys of infected WT and TIGIT-KO groups were elevated." (PMID 39109867, 2024). "Although the statistical evaluation of four samples collected much later after infection is not feasible, N-specific IFN-γ+ memory T-cells will likely become marginal in both CD8+ and CD4+ T-cells." (PMID 38543812, 2024). "However, according to our correlation analysis, it can be assumed that after mpox infection, the CD8+ T cells may contribute to a greater extent to the IFN-γ and IL-2 ELISpot response because CD8+ T cells showed significant positive correlation with ELISpot responses in contrast to CD4+ T cells." (PMID 38400115, 2024). "Compared with cell-free infection, our results show an enhancement of interactions between both CCR5-using M- and non-M-tropic viral envelope glycoproteins and CD4 and CCR5 during T cell/macrophage contact." (PMID 38400063, 2024).
infection (continued). "In L. major infection, CD4+CD25+ TREG cells recruit in dermis and, with or without IL-10 contribution, inhibit effector T cells from eliminating the parasite at the infection site." (PMID 38469319, 2024). "Pioneering mouse studies found a role for IL-12 in the early coordination of innate immunity upon infection, but IL-12 signals did not impact the ability of IAV-primed CD4 T cells to produce IFNγ." (PMID 38607077, 2024). "Convalescent patients were also distinct in that their spike-specific CD4+ T-cell levels correlated with those of CD8+ T cells, which was not the case among infection-naive patients." (PMID 38326340, 2024). "Unlike the marked decrease in CD4+ T cell counts and limited change in CD8+ T cell counts in human patients, we found that CD8+ T cells diminished significantly during infection." (PMID 37033979, 2023). "At 4 weeks post-infection, we observed a significant increase in lung infiltrating IL-2, IFN-γ, TNF-α, and IL-17 secreting CD4 but not CD8 T cells in the vaccinated group." (PMID 37359562, 2023). "In line with our ELISpot findings, we consistently observed a notable increase in IFN-γ production by both CD4+ and CD8+ T cells upon stimulation with P1 mRNA, regardless of participants' infection status." (PMID 38051989, 2023). "More generally, it needs to be considered that the forces driving memory T cell diversification are likely different in infection versus vaccination settings, do not equally apply to CD8+ and CD4+ responses, and also depend on the inoculation site." (PMID 37815874, 2023). "In all cases, we found a positive association between neutralization score values and the time elapsed from infection to ART initiation and a negative correlation with CD4+/CD8+ ratios." (PMID 38276667, 2023). "Considering the ratio of CD4-CD8- T cells to T cells was less than 5% and showed no significant changes during infection, and the limitation of our flow cytometry detection channels, we used the surface expression of CD3+CD4- to label CD8+ T cells." (PMID 37033979, 2023). "This approach also diminished the infection in these mice without changes in the proportion of CD8+ and CD4+ cells." (PMID 36680271, 2023). "Of these, only three of the new CD4 and none of the new CD8 responders were confirmed as having had breakthrough infections." (PMID 37943890, 2023). "Our data presented in Supplementary Note 1, where a minute fraction (about 2%) of CD4-negative HeLa cells showed a productive infection as detected by double EGFP+Gag+ cells using RetroNectin-based, but not spinoculation-based, infection methods, suggest this." (PMID 37563144, 2023). "Since the gut mucosal area is a major site of HIV replication during primary infection, we used a CCR5-tropic GFP reporter virus to test infection in activated and memory CD4 + T cells with or without IEC stimulation." (PMID 37202790, 2023). "Numbers of CD8+ and CD4+ T-lymphocytes expressing CD69 and TRM markers were significantly increased 1 mo after infection with Lm 10403s, but not Δhly Lm mutants." (PMID 37143648, 2023). "To extend these findings, we investigated how booster vaccinations impacted spike-specific CD4+ and CD8+ T cells in donors with or without a prior history of infection with SARS-CoV-2." (PMID 38064569, 2023). "Even though the PD-L1 expression was stimulated on the macrophages during the early infection, PD-1 was not significantly stimulated on the CD3+CD4+ T-cells, accordingly, at the same time." (PMID 36668953, 2023). "When the correlation between the CD4/CD8 ratio and infection positivity was evaluated, a moderate and negative correlation was detected with HIV RNA viral load, similar to CD4, and a moderate and negative correlation was detected with CMV infection." (PMID 37887742, 2023).
infection (continued). "Moreover, non-pathogenic infections do not reveal microbial translocation, as shown by lack of LPS or sCD14 in the plasma of SIV- infected RMs or AGMs, and experimentally induced immune activation with LPS in natural hosts shows significantly increased virus replication and CD4+ T-cell depletion." (PMID 36672667, 2023). "Infection with Pb ANKA or administration of letrozole, testosterone, or letrozole + testosterone did not change the population of CD3+CD4+ cells in either group." (PMID 37384220, 2023). "Infection increased the frequencies of activated CD3+ and CD4+ T cells, but these frequencies were not increased further by SCFA." (PMID 37865711, 2023). "The expression of the pro‐survival molecules CD127 and Bcl2 was examined in EYFP+ cytokine negative CD4 T cells and those expressing IFN‐γ, IL‐2 or TNF 40 days post‐infection." (PMID 37490492, 2023). "We found that hla expression durably reduces the number of DCs and CD4+, CD8+, and γδ T cells in dLNs during and following infection, but it is not clear how these local effects impact systemic vaccine responsiveness." (PMID 36693884, 2023). "Our results showed that bacteria-specific CD4+ T cells producing IL-17A, but not those producing IFN-γ, were decreased in coinfection compared with bacterial single infection." (PMID 37222516, 2023). "Intriguingly, while microglia promote IFN-γ production by CD4+ T cells, they do not express I-A/1-E (MHC-II) or H2-Aa, H2-Ab1, H2-DMa and H2-Eb1 (MHC-II molecules) during infection." (PMID 37016414, 2023). "Considering the correlation between the CD4/CD8 ratio and infection positivity, a moderate negative correlation was determined with HIV RNA viral load and CMV infection." (PMID 37887742, 2023). "We show that, unlike IFNγ+ T cells, AIM+ virus-specific CD4+ and CD8+ TSCM are more adequate markers of T cell memory, even beyond 18 months post-infection." (PMID 37046496, 2023). "There was no drop of CCR6 + T cells in IEC co-culture without infection, suggesting the drop was not due to IEC stimulation of CD4 + T cells only." (PMID 37202790, 2023). "Thus, although CD4+ T cells are not directly involved on bacterial killing, they can facilitate S. aureus clearance by increasing the recruitment of phagocytic cells to the site of infection and by enhancing their antimicrobial activity via the production of cytokines such as IFN-γ and IL-17." (PMID 37480485, 2023). "To determine whether the cells present at the site of infection in the peritoneal cavity of immunized mice are functioning as bona fide MDSCs, we next measured their ability to inhibit the antigen nonspecific proliferation of CD4+ T cells, the gold standard assay for MDSC suppressor function." (PMID 37681975, 2023). "From these findings, in the presence of active CD4 T cell response to M. ah in vaccinated mice, the absence of CD8 T cell response did not seem to stop the reduction in infection burden." (PMID 37359562, 2023). "Within the lung tissue, there were no increases in the numbers of Ifnγ+ CD4 and CD8 T cells 5 days after infection." (PMID 37842651, 2023). "To determine the impact of PASC on T cell immunity, we first analysed the relative percentages of CD4+ and CD8+ T cells within the T lymphocyte population six months after infection in both PASC and non-PASC compared to healthy controls (HC)." (PMID 36997530, 2023). "We found that the frequency and absolute number of CD4+ and CD4+ CD25+ T-cells did not change following anti-Gr1 treatment during the acute phase (96 h) of infection." (PMID 36776848, 2023). "Here, we showed that intranasal infection with BCG generates mycobacteria specific CD4 TEM and TCM, with frequencies of Acr-specific, but not Ag85B-specific, Th1 CD4 TCM and TEM populations increased by a single dose of both candidate vaccines." (PMID 38130713, 2023).